NF2 (NF2, moesin-ezrin-radixin like (MERLIN) tumor suppressor)
Diseases named in the same sentence as NF2 in open-access papers (continued):
Sharing a sentence is not in itself a finding about the gene and the disease.
meningioma (continued). "A recent trial utilizing the dual mTORC1/mTORC2 inhibitor AZD2014 for patients with NF2 with progressive or symptomatic meningiomas had a significant number of patients withdraw prior to study completion due to intolerable side effects (NCT02831257)." (PMID 34885143, 2021). "The highest average scores for NF experts deciding the ‘need for new treatment’ were for malignant peripheral nerve sheath tumour (MPNST) and high grade glioma (HGG) for NF1; meningioma for NF2 and pain for SWN." (PMID 33903738, 2021). "Analysis of 6 meningiomas in patients with NF2 who were treated with everolimus for progressive vestibular schwannomas showed prolonged time to progression of the meningiomas from 5.5 months pretreatment to more than 12 months on therapy." (PMID 34885143, 2021). "PIK3CA mutations are found in 4–7% of meningiomas and often cooccur with TRAF7 mutations but are exclusive of NF2, AKT1, and SMO mutations." (PMID 33801089, 2021). "Otherwise, radiation-induced meningiomas often present NF2 alterations and deficit of DNA double strand repair genes." (PMID 34679551, 2021). "In these studies, we undertook an unbiased, systems based approach to ultimately identify brigatinib as a novel monotherapy for the treatment of NF2 related schwannomas and meningiomas." (PMID 34264955, 2021). "In addition, through the analysis of familial genes of meningioma pathogenesis, it is found that there are a few genes that possess meningioma susceptibility but do not have NF2 gene mutations in the family, so in addition to NF2, there should be the presence of other mutated genes." (PMID 33673851, 2021). "A phase 2 clinical trial is also looking at NF2 specific molecular targets via a FAK inhibitor on NF2 mutant meningiomas (NCT02523014/A071401)." (PMID 34944845, 2021). "While 6% of meningiomas possess TERT promoter mutations, nearly 80% of TERT mutations in meningioma co-occur with NF2 mutations and are associated with higher tumor grade and significantly decreased tumor-free progression." (PMID 33445724, 2021). "This association is illustrated by two patients: patient (P20) with NF1 had an astrocytoma in the brain stem, and patient P25 with NF2 had a meningioma and bilateral acoustic neuromas." (PMID 34325699, 2021). "Overall, these results confirm the high frequency of genetic variants of the NF2 gene and to a less extent also of the PTEN, SMO, and POLR2A genes, in WHO grade 1 meningiomas." (PMID 34868937, 2021). "HDACs are an important epigenetic mechanism in meningiomas, in part, because of their regulation of the Akt pathway, which is affected by the inactivation of NF2." (PMID 34300316, 2021). "Meningiomas are the second most common tumor identified in patients with NF2, found intracranially in approximately 45–80% of patients and in the spinal axis in 20%." (PMID 34885143, 2021). "While often grouped together into the inclusive subgroup of non-NF-2 mutations, genomic and proteomic analyses have allowed for a more nuanced and rational classification of the heterogeneous non NF-2 genes involved in meningioma tumorigenesis." (PMID 34638590, 2021). "Alterations in the tumor suppressor gene NF2 located on chromosome 22q are the most common finding in meningiomas occuring in adults." (PMID 34495383, 2021). "Secretory meningiomas have been defined based on combined pathogenic variants of KLF4 and TRAF7 mutually exclusive of the PI3K pathway or NF2." (PMID 33262459, 2021). "Further, approximately 90% of sporadic schwannomas and 60% of sporadic meningiomas, the most common intracranial tumor in humans, have inactivation of NF2." (PMID 34264955, 2021). "Most NF2 patients also develop additional cranial, spinal, and peripheral nerve schwannomas, along with meningiomas, ependymomas, and astrocytomas." (PMID 33604573, 2021).
meningioma (continued). "For example, OGN promotes meningioma cell proliferation by interacting with other drivers of tumor development, including neurofibromatosis 2 (NF2) and mammalian target of rapamycin (mTOR)." (PMID 33622177, 2021). "Alterations in the tumor suppressor gene NF2 were the first discovered genetic etiology of meningiomas." (PMID 34778063, 2021). "We next performed mRNA sequencing of 15 tumor samples within the specific clear cell cluster and 12 NF2-mutant meningioma samples for comparison." (PMID 33319313, 2021). "In this review, we aim to encompass meningiomas and vestibular schwannomas as they pertain to NF2 by assessing molecular genetics, common tumor types, and tumor pathogenesis." (PMID 33445724, 2021). "The early and typical features of NF2 are meningiomas, ocular abnormalities, or skin plaques in children." (PMID 33767727, 2021). "NF2 shows as nervous system tumors (schwannomas involving the vestibular nerve or other regions of the nervous system, meningiomas, ependymomas, astrocytomas, and neurofibromas), peripheral neuropathy, ophthalmological lesions, and cutaneous lesions." (PMID 34670599, 2021). "The phase 2 CEVOREM trial for recurrent meningiomas utilizing everolimus and octreotide, given the strong expression of the sst2 somatostatin receptor in meningiomas, also included patients with NF2." (PMID 34885143, 2021). "Through a combination of high throughput screens, preclinical in vivo modeling, and evaluation of the kinome en masse, we identified actionable drug targets and efficacious experimental therapeutics for the treatment of NF2 related schwannomas and meningiomas." (PMID 34264955, 2021). "Recurrent YAP1-MAML2 fusions have been reported in poroma and porocarcinomas, pediatric NF2‐wildtype meningioma, composite and retiform hemangioendothelioma, glioblastoma, nasopharyngeal carcinoma and ovarian cancer cell lines." (PMID 34354947, 2021). "For example, it has been reported that chrysophanol inhibits the osteoglycin/mTOR and activates NF2 signaling pathways to reduce viability and proliferation of malignant meningioma cells." (PMID 34519612, 2021). "NF2 (15/32 tumors, 47%) gene was the most frequently showed non-synonymous and/or synonymous genetic variants among WHO grade 1 meningiomas." (PMID 34868937, 2021). "Inhibiting FAK with GSK2256098 is currently under investigation in a phase 2 trial for patients with NF2-altered meningioma (NCT02523014/A071401)." (PMID 31161239, 2020). "Therapeutic effects and biological mechanisms of the identified compound, ICG-001, in NF2-mutant meningiomas were further characterized in vitro and in patient-derived xenograft (PDX) models." (PMID 32642722, 2020). "For instance, the most common CNAs in meningiomas involve chromosomes 22q, which are found in the neurofibromatosis 2 (NF2) gene." (PMID 32670372, 2020). "While only approximately 5% of patients with a meningioma in the general population will have multiple lesions, 20% of such patients are diagnosed with NF2." (PMID 31161239, 2020). "We also observed an enrichment in alterations in CDKN2A/B, KDM6A, ARID1A, PTEN, FBXW7, and SUFU in comparison with NF2-wt meningiomas." (PMID 33087175, 2020). "Our results were consistent with earlier studies that reported mutations in NF2, SMO, and AKT1 genes in atypical meningiomas, and we also observed mutations in MYBL2, a gene that was recently discovered." (PMID 32742192, 2020). "We also provide further evidence that ICG-001 inhibits proliferation of NF2-mutant meningioma cells at least partly through attenuating the FOXM1-mediated Wnt/β-catenin signaling." (PMID 32642722, 2020).
meningioma (continued). "Other distinctive lesions frequently encountered in NF2 include multiple schwannomas of cranial, spinal, or peripheral nerves, meningiomas, ependymomas, and ocular lesions." (PMID 31161239, 2020). "Neurofibromin 2 (Nf2, also called merlin) is originally identified as a tumor suppressor factor and involved in various cancers, including schwannoma, meningioma, and malignant mesothelioma." (PMID 32422606, 2020). "To validate focused drug screening results in vivo, we tested ICG-001 as a single agent for patients with NF2-mutant meningioma (M8 and M9) using PDX models as well as safety considerations measuring by animal weight." (PMID 32642722, 2020). "On the other hand, meningiomas with NF2 inactivation are genomically less stable and localize to the brain hemispheres." (PMID 32244473, 2020). "To investigate the potential of ICG-001 for treating NF2-mutant meningiomas, we performed another testing with ICG-001 in ten high-grade patient-derived cell lines." (PMID 32642722, 2020). "This schema was amended (NIH 1991 and Manchester 1992) with the introduction of additional criteria, to include patients lacking bilateral vestibular schwannomas or a family history of NF2, but who were diagnosed with multiple schwannomas and/or meningiomas." (PMID 31161239, 2020). "Additional studies exploring the biology and treatment of NF2-mutant meningiomas will certainly be required in the future." (PMID 32642722, 2020). "A focused drug screen showed that NF2-mutant meningioma cells are especially sensitive to ICG-001, a cAMP-response elemen (CREB)-binding protein inhibitor, both in vitro and in vivo." (PMID 32642722, 2020). "When present, meningiomas in NF2 patients are often multiple, which contributes significantly to morbidity and mortality." (PMID 32724039, 2020). "Focussing on WHO grade I meningiomas with different defined genotypes, NF2 meningiomas displayed a tendency towards higher M2 macrophage infiltrates when compared to AKT1 E17K-mutated tumours." (PMID 32070062, 2020). "A PTK2/FAK inhibitor GSK2256098 is currently being tested in a clinical trial with recurrent meningiomas carrying inactivated NF2 (NCT02523014)." (PMID 32724039, 2020). "Most NF2 related meningiomas present as a fibrous or transitional phenotype, which are the most common histopathological subtypes of meningioma and are generally more aggressive than sporadic tumors." (PMID 33194703, 2020). "In this study, we screened 171 meningiomas using endpoint genotyping and linked mutations in AKT1 E17K and NF2 in grade I meningiomas to macrophage infilitration using four-colour flow cytometry and immunohistochemistry." (PMID 32070062, 2020). "NF2 complete inactivation is the main, and possibly only, genetic event leading to meningioma initiation in NF2 patients." (PMID 32724039, 2020). "Genomics studies have confirmed the importance of mutations such as NF2, TRAF7, KLF4, AKT1, SMO, PI3KCA, and POLR2A in the occurrence and development of meningiomas." (PMID 32974188, 2020). "We identified NF2 mutations, chromatin remodeling and DDR gene mutations as independent prognostic markers for aggressive course, and described the first case of meningioma developing in a patient with ATM germline cancer-predisposing mutation." (PMID 31963394, 2020). "The clinical significance of the mutations of NF2, KLF4, and TRAF7 were proven in meningiomas, and studies have shown a significant association between mutations and specific locations." (PMID 32974148, 2020). "Bi-allelic CDKN2A/B deletions occurred in 93/472 of all NF2-mutant (19.7%) versus 30/377 in NF2-wt meningiomas (8.0%) (p = 0.0001)." (PMID 33087175, 2020). "A 20-agent library covering a wide range of meningioma relevant targets was tested using meningioma cell lines IOMM-Lee (NF2 wildtype) and CH157-MN (NF2 deficient)." (PMID 32642722, 2020). "Our findings also provide the rationale for the future development of novel mechanism-based therapies for NF2-mutant meningiomas." (PMID 32642722, 2020).
meningioma (continued). "Another limitation of this study is that modest number of NF2 patients and meningiomas that was analyzed rendered it underpowered; however, similar limitations are frequently encountered in the research of rare genetic disorders." (PMID 32724039, 2020). "This study highlights the importance of ligand-mediated Wnt/β-catenin signaling as well as its drugable potency in NF2-mutant meningioma." (PMID 32642722, 2020). "In a recent high-throughput kinome screen in NF2-null human arachnoidal and meningioma cells, we showed activation of EPH RTKs, c-KIT, and SFK members independent of mTORC1/2 activation." (PMID 32144278, 2020). "In contrast, meningiomas driven by the inactivation of NF2 tend to localize primarily to the convexity." (PMID 33194703, 2020). "Bi-allelic NF2 inactivation is the most common and most studied genetic alteration found in meningiomas." (PMID 32245394, 2020). "NF2-associated meningiomas frequently occur at an earlier age than sporadic tumors, and presentation with meningioma in the pediatric setting should raise suspicion for NF2." (PMID 31161239, 2020). "Our results thus advocate ICG-001 as a promising agent for further preclinical evaluation in NF2-mutant meningiomas." (PMID 32642722, 2020). "Biallelic NF2 inactivation also occurs in various sporadic tumors, especially in schwannomas, meningiomas, malignant mesothelioma, and ependymomas." (PMID 31312020, 2019). "Cell proliferation of wild-type NF2 malignant meningioma IOMM-Lee cells was notably reduced when treated with either drug." (PMID 31730023, 2019). "Of note, the NF2—OXCT1 fusions all occurred in meningiomas that progressed to higher grade or were secondary to progression." (PMID 31039818, 2019). "That was the case for Neurofibromatosis Type II (NF2) and STAG2 that was shown to predispose for MISME (“Multiple Inherited Schwannomas, Meningiomas, and Ependymomas”) Syndrome and Ewing sarcoma respectively." (PMID 31105870, 2019). "Taken together, these findings suggest that NF2 mutant meningiomas tend to be slower growing, more indolent tumors than meningiomas harboring other genomic alterations." (PMID 31191822, 2019). "Multiple meningiomas occur in 5% of schwannomatosis cases, but only in association with SMARCB1 mutations, hinting at a potential interaction between NF2 and SMARCB1 in meningioma pathogenesis, later validated in NGS studies." (PMID 31652973, 2019). "Next, we focused on the most prevalent genetic alterations reported in meningiomas so far, including NF2, SMARCB1, as well as TRAF7, AKT1, SMO, KLF4, PIK3CA, and TERT in non-NF2 mutated meningiomas." (PMID 31470906, 2019). "Next, we focused on the most common genetic alterations reported so far in meningiomas, including the NF2, SMARCB1, as well as TRAF7, AKT1, SMO, KLF4, PIK3CA, and TERT in non-NF2 mutated meningiomas." (PMID 31470906, 2019). "Next-generation sequencing studies have provided a framework for an increasingly sophisticated categorization of meningiomas into two groups: non-NF2 mutants and NF2 mutants." (PMID 31652973, 2019). "Execution of high throughput genomic analysis in large multi-center studies are needed to further elucidate the role of NF2 within the complex phenotypic manifestations of meningiomas." (PMID 31191822, 2019). "Despite genetic alterations of the NF2 gene, recent studies revealed other important alterations in non-NF2 meningiomas." (PMID 31470906, 2019). "The most common genetic alteration found in meningiomas involves the tumor suppressor neurofibromatosis gene 2 (NF2) on chromosome (chr) 22q." (PMID 31470906, 2019). "Although NF2 clearly illustrates that there are familial inheritance tendencies for meningioma, the majority of meningiomas in humans occur as sporadic tumors." (PMID 31788444, 2019). "One study of 18 radiation-induced meningiomas found that nearly all had chr22q LOH, with a majority also having NF2 loss via fusion events." (PMID 31652973, 2019).
meningioma (continued). "So far, none of the drugs tested in vitro or in pre-clinical or clinical trials has been effective on NF2 meningioma." (PMID 31730023, 2019). "The TIMP3 gene is located on chromosome 22q12; interestingly, the majority of meningiomas had deletions in this chromosome region, which also contained the NF2 tumor suppressor gene." (PMID 30279357, 2018). "MPMNs reportedly share the status of neurofibromatosis (NF)-2 gene with meningiomas of the central nervous system." (PMID 30542514, 2018). "It has also been suggested thatprimary ectopic meningiomas of the head and neck are related to neurofibromatosis,particularly NF2." (PMID 31489219, 2018). "Neurofibromatosis 2 (NF2) is a rare tumor suppressor syndrome that manifests with multiple schwannomas and meningiomas." (PMID 29897904, 2018). "We used fluorescence in situ hybridization to explore the status of the NF-2 gene in MPMNs and compare it with that of CNS meningiomas." (PMID 30542514, 2018). "We have reported here two deletions of NF-2 gene in two MPMNs and one deletion of NF-2 gene in two CNS meningiomas." (PMID 30542514, 2018). "The possibility of an ectopic meningioma should be considered if a lesion isfound in the parapharyngeal space of a patient with NF2." (PMID 31489219, 2018). "In most non-NF2 patients, meningiomas and schwannomas are effectively treated with surgery or radiation therapy." (PMID 29897904, 2018). "Weissferdt and colleagues explored the status of neurofibromatosis (NF)-2 gene in pleuropulmonary meningothelial proliferations and compared it with that of meningiomas of the central nervous system (CNS)." (PMID 30542514, 2018). "We used a commercially available locus-specific probe for the NF-2 region to analyze whole tissue sections of two MPMNs and two CNS meningiomas by fluorescence in situ hybridization." (PMID 30542514, 2018). "Inactivation of the Nf2 gene in the germ line leads to the development of benign schwannomas, meningiomas and gliomas, tumors that endanger the patient by compressing important structures of the nervous system." (PMID 29715273, 2018). "Second, there is evidence regarding the strong involvement of Neurofibromatosis-2 (NF2) gene, as a direct marker of meningioma specific tumor suppressor, in the etiology of meningioma." (PMID 30687635, 2018). "Importantly, the findings of low PR and NF2 expression associated with higher risk of meningioma may signify potential clinical marker to be used as to whether one individual using progesterone-contained hormonal contraception is at higher risk of developing meningioma in the future." (PMID 30687635, 2018). "The hope was that a single agent would have activity based on merlin status across tumor types making it clinically feasible for patients to take one agent to address both their NF2 driven schwannomas and meningiomas." (PMID 29897904, 2018). "Over 60% of NF2 inactivated meningioma is reported to be located in the calvarium, including convexity of the skull, parasagittal region, and falx cerebri." (PMID 30082628, 2018). "NF2 mutant meningiomas are in all grades including WHO grade II and III whereas SMO, TRAF7, TRAF7/AKT1 and KLF4 meningiomas tend to be WHO grade I." (PMID 30082628, 2018). "RUNDC3B, SCG2, SLC1A3, EXT1 (as well as RHOBTB3, TSPAN7, CAV2, MLPH) were part of the NF2/SMARCB1 expression subclass of a recent study on genomic profiling of meningioma." (PMID 29662628, 2018). "Here, we present an in-depth genomic study of grade I and grade II meningiomas that resided in close proximity in the brain of an NF2 patient." (PMID 28193203, 2017). "In this study, the authors perform an exome, methylation and RNA-seq analysis of 31 cases of radiation-induced meningioma and show NF2 rearrangement, an observation previously unreported in the sporadic tumors." (PMID 28775249, 2017). "Both tumors had second copy inactivation of NF2, confirming the central role of the gene in meningioma formation." (PMID 28193203, 2017).